ONECUT2 (one cut homeobox 2)
Diseases named in the same sentence as ONECUT2 in open-access papers (continued):
Sharing a sentence is not in itself a finding about the gene and the disease.
tumor (continued). "We observed significant upregulation of miR-200b (p = 0.003) and ONECUT2 (p = 0.018) in the tumour tissue of CRC pT3 compared to the corresponding normal mucosa, as well as downregulation of CDKN1B (p = 0.013)." (PMID 36140249, 2022). "One cut homeobox 2 (ONECUT2, also named OC2) is related to the proliferation, motility and differentiation of tumor cells." (PMID 34253241, 2021). "In lymph node metastases compared to the invasive front of the tumor, ONECUT2 and SOX2 were down-regulated, while PTPN13, TGFB2, ZEB2, RND3 and CDKN1B were up-regulated." (PMID 34046357, 2021). "ONECUT2 overexpression synergizes with hypoxia to drive NE plasticity and aggressive tumor biology in NEPC." (PMID 30655535, 2019). "Consistently, silencing ONECUT2 using two different shRNAs significantly reduced subcutaneous tumor growth in PC3 xenografts." (PMID 30655535, 2019). "To determine the effect of ONECUT2 on tumor hypoxia, we analyzed hypoxia levels using pimonidazole (PIMO) staining in PC3 and NCI-H660 xenografts with and without silencing of ONECUT2." (PMID 30655535, 2019). "By using in vitro cell line models, we reveal that ONECUT2 regulates the aggressive tumor biology in NEPC, at least partially through activating SMAD3-HIF1α signaling." (PMID 30655535, 2019). "Since HIF1α plays a central role in transcriptional response to hypoxia and ONECUT2 regulates hypoxia signaling and tumor hypoxia, we next sought to characterize the interplay between HIF1α and ONECUT2 at transcriptional regulation." (PMID 30655535, 2019). "A risk-associated variant at rs7463708 increased binding of ONECUT2, a transcriptional factor, at a distal enhancer that loops to the lncRNA-PCAT1 promoter and thus promotes cancer cell proliferation and tumor growth." (PMID 30518759, 2018). "Onecut2 (OC2) plays a crucial regulatory role in tumor growth, metastasis, and angiogenesis." (PMID 41513612, 2026). "Targeting ONECUT2 for therapeutic ends may lead to unfavorable side effects; on the other hand, ONECUT2-dependent tumor hypoxia can be more effective for NEPC patients." (PMID 38674385, 2024). "ONECUT2 shows promise for tumor diagnosis, prognosis, and treatment." (PMID 38997271, 2024). "Regulator of NE tumour genes, coexpressed and regulated by ONECUT2, increased with hypoxia." (PMID 39682746, 2024). "Accumulating evidence indicates that ONECUT2 expression significantly influences the development and progression of malignant tumors, suggesting that ONECUT2 may have significant potential for tumor diagnosis, prognosis, and treatment." (PMID 38997271, 2024). "Similarly, we observed significant upregulation of miR-200b (p = 0.002) and ONECUT2 (p = 0.028) in CRC pT4a tumour tissue with serosal invasion compared to the corresponding normal mucosa." (PMID 36140249, 2022). "Although not differentially expressed between pT3 and pT4a, expression of ONECUT2 increased with the pT stage and might be thus indirectly related to local tumour spread." (PMID 36140249, 2022). "TGFBR3 belongs to the functional process GO:0071559 (the response to transforming growth factor β) along with ACVR2B (the activin receptor type 2B) and the transcription factor ONECUT2 (one cut domain family member 2) involved, respectively, in cell signaling and tumor growth." (PMID 35740429, 2022). "In addition, PTPN13 seems to be one of the important regulators involved in serosal invasion, and ONECUT2 in tumour growth." (PMID 36140249, 2022). "Indeed, qRT-PCR and IHC assay showed that ONECUT2 level was increased in tumor tissues compared to normal tissues." (PMID 34253241, 2021). "An emerging role of ONECUT2 in tumor biology has recently been recognized." (PMID 34046357, 2021). "In addition, high expression of ONECUT2 was correlated with bad prognosis in tumor samples of PDAC patients." (PMID 32908137, 2020).
tumor (continued). "Importantly, silencing of ONECUT2 in PC3 xenografts almost completely abolished the tumor inhibition effect of TH302, and overexpression of ONECUT2 sensitized the V16A xenografts to TH302." (PMID 30655535, 2019). "Furthermore, AUTS2 and PCGF5 may (de)regulate ONECUT2 activity via chromatin modifications in the tumor cells." (PMID 38474011, 2024). "In addition, similar to our results in CRC, they noted a correlation of ONECUT2 with tumour stage." (PMID 36140249, 2022). "Targeting ONECUT2 itself might be problematic due to its expression also in normal tissues, such as brain, liver, and pancreas but promising results have been observed when targeting ONECUT2-dependent tumor hypoxia." (PMID 33572108, 2021). "Therefore, direct targeting of ONECUT2 may lead to unfavorable side effects, while targeting of ONECUT2-dependent tumor hypoxia could be a more convenient and optimal choice for NEPC patients." (PMID 30655535, 2019). "ONECUT2 can be directly targeted with a novel small molecule, CSRM617, that was demonstrated to suppress tumor growth and metastasis in vivo." (PMID 41545903, 2026). "In vitro experiments showed that compared with 2D GC cell culture, the expression of ONECUT2 protein and stemness-related markers CD44, SOX9, SOX2, and LGR4 simultaneously increased in 3D tumor stem cell spheroid culture." (PMID 38997271, 2024). "Cox regression analyses were performed to identify independent clinical prognostic parameters to construct a combined nomogram which includes the expression of CERCAM, MIA2, HS6ST2, ONECUT2, SOX12, TMEM132A, pT stage, tumor size and ISUP grade." (PMID 35954418, 2022). "The results revealed that the mRNA expression levels of DLX4, FBN1, HIC1, HOXB9, ONECUT2, and SIX1 were significantly different between tumor samples and normal tissues, which were consistent with the results from TCGA." (PMID 35095892, 2021). "Several recent studies have proposed various mechanisms of NEPC development, including modifications of the tumor microenvironment with epigenetic effects on cancer cells, as well as reports of molecular drivers such as SRRM4, FOXA1 and ONECUT2." (PMID 32252342, 2020). "Down-regulation of the miR-200 family at the invasive front in comparison to the central part of tumour was observed as well as a correlation of expression of miR-200b, CDKN1B, ONECUT2 and ZEB2 expression to nodal metastases." (PMID 31623346, 2019). "In line with the tumor inhibition effects, PIMO staining in PC3 xenografts was much stronger than in V16A xenografts, and ONECUT2 knockdown reduced tumor hypoxia in PC3 xenografts, while ONECUT2 overexpression increased tumor hypoxia in V16A xenografts." (PMID 30655535, 2019). "Gene Set Enrichment Analysis (GSEA) revealed that ONECUT2 targets genes were enriched with cell cycle related gene sets such as G2M_CHECKPOINT and E2F_TARGETS, in concordance with the function of ONECUT2 in regulating PC3 cell proliferation and tumor growth." (PMID 30655535, 2019). "Here they report ONECUT2 to drive NEPC tumorigenesis via regulation of hypoxia signaling and tumor hypoxia, and find hypoxia directed therapy to be effective in NEPC." (PMID 30655535, 2019). "Indeed, a small-molecule inhibitor of ONECUT2, CSRM617, exhibited direct binding to the protein and successful tumour growth inhibition in vivo." (PMID 39682746, 2024). "The result confirmed that the expression levels of ONECUT2, IGF2BP1, and ANXA2 were significantly elevated in non-tumor tissues compared to normal tissues (P = 0.0116, P = 0.0380 and P = 0.0145, respectively), and further elevated in HCC tissues (P = 0.0270, P = 0.0003 and P < 0.0001, respectively)." (PMID 26547929, 2015). "ONECUT2 is a member of the ONECUT transcription factor family that was shown to promote epithelial-mesenchymal transition (EMT), one of the well-defined processes during tumor invasion and distant metastasis." (PMID 26547929, 2015).
tumor (continued). "However, while being upregulated in all stages of the cancer progression through the bowel wall, ONECUT2 does not seem to contribute significantly to the invasion through the serosal membranes, but rather is responsible for the continuous growth of tumours." (PMID 36140249, 2022). "However, because, in comparison with normal mucosa, the expression of Onecut2 mRNA was upregulated in the bulk tumor of patients with GC without peritoneal involvement but downregulated in those showing PC, we have focused our attention on LIFR." (PMID 35847866, 2022). "Additionally, the synergistic interaction between ONECUT2 and hypoxia has led to the investigation of an alternative therapeutic strategy involving the use of the hypoxia-activated prodrug TH-302, which reduces NEPC tumor growth in both xenograft and PDX (patient-derived xenografts) models." (PMID 37761978, 2023). "Among all genes tested, ONECUT2, IGF2BP1, and ANXA2 were aberrantly upregulated in tumor tissues compared to non-tumor tissues." (PMID 26547929, 2015). "The expression levels of ONECUT2, IGF2BP1, and ANXA2 were significantly upregulated in tumor tissues compared with non-tumor tissues, which suggested that they might play an oncogenic role in HCC development." (PMID 26547929, 2015).
cancer (39 papers, 2013 to 2026). A tumor composed of atypical neoplastic, often pleomorphic cells that invade other tissues. "Finally, ONECUT2 is upregulated in the BC_sBRCA2 group suggesting an association with cancer stem cell traits and expression of stemness-associated genes." (PMID 33525353, 2021). "Genomic Set Enrichment Analysis (GSEA) revealed enrichment of the TNFα signaling pathway via the NFκB and mTORC1 signaling gene clusters within cancer cells expressing ONECUT2." (PMID 38997271, 2024). "Our analysis revealed a significant association between ONECUT2, PI3K/AKT, and other cancer-related pathways." (PMID 38997271, 2024). "Several studies have highlighted the role of ONECUT2 in regulating stemness in various malignant tumors and, in turn, influencing their progression." (PMID 38997271, 2024). "This is found effective in reducing proliferation and tumor volume by inducing apoptosis of cancer cells with high ONECUT2 expression." (PMID 36711033, 2023). "Conversely, the downregulation of these miRNAs or the upregulation of One Cut Homeobox 2 expression abolished the cancer stem-like cell-activating effect of extracellular vesicles from chemotherapy-treated BRCA cells." (PMID 37647033, 2023). "The role of ONECUT2 in cancer progression has been found to be elevated in different types of cancer, including CRC." (PMID 36140249, 2022). "As expected, the expression of ONECUT 2 gene was significantly (P < 0.05) low in cancer tissues and cell lines." (PMID 35874630, 2022). "As a novel mechanism of drug resistance, chemotherapy has been shown to stimulate tumor cells to secrete exosomes enriched in ANXA6, which deliver heterogeneous and enhance the capacity for transfer and promote cancer stemness by targeting ONECUT2." (PMID 33823894, 2021). "Overexpression of ONECUT2 facilitates cancer progression with roles in proliferation, invasion, and angiogenesis." (PMID 34839358, 2021). "For example, it was recently shown that chemotherapy induces the exosome delivery of miR-9-5p, miR-203a-3p and miR-195-5p, which co-target ONECUT2 to promote cancer stemness." (PMID 33823894, 2021). "It has been reported that ONECUT2 acts a critical position on CRC gene network and is significantly associated with the development of cancer." (PMID 32377269, 2020). "Among the genes with increased 5hmC density in PDAC were those related to pancreas development (GATA429, GATA629, PROX130, ONECUT131, and MEIS232) and/or implicated in cancer (YAP133, TEAD133, PROX134, ONECUT2, ONECUT1, and IGF1)." (PMID 33077732, 2020). "ONECUT2 was the most commonly upregulated TF, showing increased mRNA levels relative to normal in 15 cancer types." (PMID 30655535, 2019). "Because loss of cell-cell contact and establishment of cell-substrate interaction are critical steps in the invasion of cancer cells, we further tested the changes in cell-matrix contact in response to ONECUT2 overexpression." (PMID 31882655, 2019). "Heatmap representation of unsupervised clustering analysis revealed distinct DNA methylation patterns in adjacent-normal prostate and PCa lesions with statistically significant cancer-specific DNA hypermethylation (p < 1.9E-16 and 1.2E-15, respectively) in 7–8 CpGs in the ONECUT2 locus." (PMID 41545903, 2026). "ONECUT2 is critical in various biological processes and diseases, including liver development, insulin secretion, spinal neuron development, and acquisition and maintenance of cancer stemness." (PMID 38997271, 2024). "ONECUT2 was characterized as a transcription factor that participates in cancer development." (PMID 37444485, 2023). "Elevated expression levels of ONECUT2 have been reported in various cancers, particularly in NEPC." (PMID 36711033, 2023). "ONECUT2 has early been implicated in EMT and cancer cell invasion in colorectal cancer." (PMID 31882655, 2019).
cancer (continued). "When single-cell-level viability was quantified from the multiplexed (i.e., cell count plus viability) screens, it provided information on both the susceptibility and resistance response of cancer cells to druggable target knockdowns such as CYP2A6 and ONECUT2 genes." (PMID 31467349, 2019). "Therefore, ONECUT2 overexpression marks the onset of cancer progression and metastasis." (PMID 36711033, 2023). "ONECUT2 may play a critical role in pan-cancer-wide tumorigenesis." (PMID 35205261, 2022). "Additionally, ONECUT2 shows significant upregulation in cancers derived from multiple human tissues, indicating that ONECUT2 may play a critical role in tumorigenesis pan-cancer wide." (PMID 30655535, 2019). "High expression of CERCAM, HS6ST2, ONECUT2, SOX12 and TMEM132A and low expression of MIA2 related to poor outcomes for progression-free survival and cancer-specific survival." (PMID 35954418, 2022). "To identify the regulatory pathways involved in ONECUT2-mediated HCC metastasis, we conducted a human Cancer PathwayFinder RT2 Profiler PCR Array following ONECUT2 overexpression." (PMID 34839358, 2021). "For instance, miR-429 mediated suppression of EMT has also been correlated with miR-429 directly targets Onecut2, BMI-1 and E2F3, MiR-429 enhances cancer cell apoptosis under chemotherapy by targeting Bcl-2 and AP-2α." (PMID 27058893, 2016). "In addition, we also identified two well-known neuroendocrine genes, ONECUT2 and SRRM4, that demonstrated cancer-specific gene body DNA methylation alterations, and which also positively correlated with gene expression in MCC." (PMID 34399838, 2021). "To fill this knowledge gap, we performed a pan-cancer analysis of poorly differentiated NET and non-NETs, and identified transcription factor ONECUT2 as a potential master regulator of poorly differentiated NETs." (PMID 30655535, 2019).
adenocarcinoma (7 papers, 2019 to 2025). A common cancer characterized by the presence of malignant glandular cells. "A significantly higher level of ONECUT2 expression was found in NEPC compared to adenocarcinoma, and conversely, a reduction in ONECUT2 expression was shown to decrease NE marker gene expression." (PMID 35582526, 2022). "FOXA1, another modulator that normally inhibits NE differentiation, is suppressed by ONECUT2 during transdifferentiation of adenocarcinoma into NEPC." (PMID 35582526, 2022). "A decrease in REST expression leads to upregulation of ONECUT2 mRNA and allows for the transition from adenocarcinoma to NEPC." (PMID 35582526, 2022). "We determined that ONECUT2 expression is significantly increased in CRPC compared to primary adenocarcinoma, while the largest difference is observed between NEPC and adeno-CRPC." (PMID 30655535, 2019). "To further confirm its clinical relevance, we assessed ONECUT2 expression from benign prostate tissues, primary adenocarcinoma and metastatic CRPC tumors in two independent clinical cohorts and a pooled cohort of TCGA and Beltran10." (PMID 30655535, 2019). "Further examination revealed that ENZ treatment induced the expression of NR1D1/REV-ERBα and LP drivers, such as BRN2, ASCL1, FOXA2, and ONECUT2, in a dose and time-dependent manner in adenocarcinoma cells, with REV-ERBα being the fastest and strongest induced among them." (PMID 41231955, 2025). "Additionally, high level of ONECUT2 in primary adenocarcinoma is a strong predictor of poor outcome as measured by biochemical recurrence-free survival in two clinical cohorts." (PMID 30655535, 2019). "ONECUT2 expression is significantly higher in clinical NEPC samples compared to benign prostate, primary adenocarcinoma and mCRPC-adenocarcinoma." (PMID 37761978, 2023). "An increase in ONECUT2 expression corresponds to upregulation of PEG10 and transition from adenocarcinoma to NEPC." (PMID 35582526, 2022).
ONECUT2 also shares sentences with these, for which no sentence is quoted: hepatocellular carcinoma (5 papers); lymph node metastasis (4); ovarian carcinoma (4); infection (3); breast tumor (2); Hematuria (2); neuroendocrine tumors (2); thyroid cancer (2); viral infection (2); Carcinoid (1); cervical adenocarcinoma (1); esophageal cancer (1); glioma (1); Hodgkins lymphoma (1); insulinoma (1); intraductal carcinoma (1); lung disease (1); lymphoma (1); multiple myeloma (1); Pituitary Adenoma (1); psychotic disorder (1); retinal degeneration (1); stomach cancer (1); trachoma (1); uterine cancer (1).